FOXM1 (forkhead box M1)
Diseases named in the same sentence as FOXM1 in open-access papers (continued):
Sharing a sentence is not in itself a finding about the gene and the disease.
colorectal cancer (continued). "More recent studies reported the ability of this miRNA to counteract cell proliferation and invasion through inhibition of DNA methyltransferase 1 in SW480 colorectal cancer cells and inhibition of the transcription factor FOXM1 in cervical cancer cells." (PMID 26919240, 2016). "Subsequently, in colorectal cancer cell lines, we showed that knocking down FOXM1 decreased HSPA5 expression, whereas overexpression of FOXM1 increased HSPA5 level." (PMID 27034162, 2016). "FOXM1 mRNA level was firstly found to positively correlate with HSPA5 in colorectal cancer and adjacent normal tissue samples." (PMID 27034162, 2016). "Several studies have shown that FOXM1 is an important inducing factor of colorectal cancer cell migration and invasion." (PMID 27034162, 2016). "A series of studies in vitro and in vivo revealed that FOXM1 possesses a tumour-stimulative function and displays high expression in several cancer types including colorectal cancer." (PMID 27034162, 2016). "Here, we found that enhancement of migration and invasion by FOXM1 was significantly attenuated by depletion of HSPA5 in colorectal cancer cell." (PMID 27034162, 2016). "We ectopically introduced siRNA against HSPA5 to FOXM1-overexpressed colorectal cancer cells respectively." (PMID 27034162, 2016). "Lastly, our results suggested FOXM1 facilitated the activities of MMP2 and 9 associated with HSPA5 in colorectal cancer cells." (PMID 27034162, 2016). "Analyses of multiple microarray datasets derived from human colorectal cancer indicated that correlation levels of FoxM1 and pituitary tumor transforming gene (PTTG1) are highly concordant (R = 0.68 ~ 0.89, p = 2.1E-226 ~ 9.6E-86)." (PMID 26264222, 2015). "These luciferase plasmids were co-transfected with FoxM1 or control plasmid into colorectal cancer cells, and promoter activity measured." (PMID 26264222, 2015). "EMSA and ChIP assays confirmed that FoxM1 directly binds to PTTG1 promoter at the −391 to −385 bp region in colorectal cancer cells." (PMID 26264222, 2015). "The researchers also found strong correlations between expression of SHH and FOXM1 and between expression of Gli and FOXM1 in colorectal cancer cells." (PMID 24325450, 2013). "Besides the cell cycle aspect, higher expression levels of FOXM1 have been known to correlate with tumor invasion, leading to poor prognosis in colorectal cancer." (PMID 39272919, 2024). "The link between miR-532-3p and FOXM1 could offer an insight on the direct tumor suppressive function exhibited by miR-532-3p in colorectal cancer, among other types of the disease." (PMID 39272919, 2024). "Also, circANKS1B regulates FOXM1 expression and promotes cell migration and invasion by functioning as a sponge of the miR-149 in colorectal cancer." (PMID 35148692, 2022). "FOXM1 inhibited the maturation of dendritic cells in colorectal cancer." (PMID 35395711, 2022). "For instance, circANKS1B could promote colorectal cancer cell invasion by functioning as a sponge of miR‐149 to regulate the FOXM1 expression." (PMID 33184989, 2020). "In addition, PTTG1 was upregulated by FOXM1 in colorectal cancer, suggesting its role in migration and invasion of cancer cells." (PMID 33173433, 2020). "FoxM1 increases the invasion and migration of colorectal cancer by binding to the HSPA5 promoter." (PMID 32035486, 2020). "Further, HER2 and FOXM1 expression has also been observed to have correlation in colorectal cancer." (PMID 33680951, 2020). "A study on colorectal cancer finds that the expression level of miR-149 in colorectal cancer tissues is significantly lower than that in adjacent normal tissues, and the expression level of miR-149 is inversely proportional to the expression level of FOXM1." (PMID 33102210, 2020). "However, little is known about the role of FOXM1 in colorectal cancer, specifically with respect to 5-FU resistance." (PMID 30728402, 2019).
colorectal cancer (continued). "In addition, miR-761 overexpression promoted the sensitivity of colorectal cancer cells to 5-FU through targeting FOXM1." (PMID 29416616, 2018). "We identified that FOXM1 was a direct target gene of miR-761 in colorectal cancer cell." (PMID 29416616, 2018). "In human basal cell carcinomas and colorectal cancer cells, FOXM1 is also a direct target of Gli1." (PMID 30208972, 2018). "We next detected FOXM1 expression in colorectal cancer tissues." (PMID 29416616, 2018). "We next decided to investigate whether the combined treatment of cetuximab and celecoxib alters the interaction of β-catenin-FOXM1 in colorectal cancer cells." (PMID 28423516, 2017). "Significantly, there was no such association between FOXM1 nuclear localization and response to treatment in samples from colorectal cancer patients treated with the anti-angiogenic drug bevacizumab." (PMID 28423516, 2017). "We and others have previously shown that FOXM1 may play an important role in the response of colorectal cancer cells to anti-EGFR treatment." (PMID 28423516, 2017). "Moreover, compared with adjacent normal tissue specimens, colorectal cancer tissue specimens exhibited higher FOXM1 mRNA levels." (PMID 27034162, 2016). "Furthermore, we found that Gli1 promotes colorectal cancer cells metastasis in a Foxm1-dependent manner by activating EMT and PI3K-AKT signaling." (PMID 27863385, 2016). "FOXM1 mRNA levels were found to positively correlate with HSPA5 in colorectal cancer." (PMID 27034162, 2016). "Additionally, FOXM1 has been found to increase colorectal cancer migration and invasion by regulating a various signal pathways, such as urokinase-type plasminogen activator receptor (uPAR) and matrix metalloproteinase 2 and 9 (MMP2 and 9) signaling pathway." (PMID 27034162, 2016). "In this study, to investigate whether endoplastic reticulum (ER) stress correlated with FOXM1 in colorectal cancer, we analysed the mRNA levels of FOXM1 and ER stress markers HSPA5 and spliced XBP1 by qRT-PCR." (PMID 27034162, 2016). "Furthermore, FOXM1 triggered colorectal cancer cell migration and invasion were involved in activities of cell-surface HSPA5." (PMID 27034162, 2016). "Furthermore, FOXM1 triggered colorectal cancer cell migration and invasion was involved in activities of cell-surface HSPA5." (PMID 27034162, 2016). "To elucidate the relationship between FOXM1 and HSPA5 expression in colorectal cancer cells, we used two siRNAs against FOXM1 as well as FOXM1b or FOXM1c lentiviral high-expression vectors to transfect two colorectal cancer cell lines, namely SW1116 and LOVO cells." (PMID 27034162, 2016). "In addition, we found that enhancement of cell migration and invasion by FOXM1 was significantly attenuated by depletion of HSPA5 in colorectal cancer cell." (PMID 27034162, 2016). "To determine whether FoxM1 modulates PTTG1 expression in colorectal cancer cells, we first examined FoxM1 expression in 61 colorectal cancer cell lines using microarray data derived from CCLE (Cancer Cell Line Encyclopedia)." (PMID 26264222, 2015). "PTTG1 is required for FoxM1 to promote colorectal cancer cell migration and invasion." (PMID 26264222, 2015). "However, the precise function and internal mechanisms of FOXM1 in colorectal cancer cells EMT and metastasis remain still indistinct." (PMID 25935853, 2015). "All our in vitro assays suggest a pivotal role for the FOXM1 in the metastasis progression of colorectal cancer and FOXM1 silencing could efficiently control the CRC cells metastasis." (PMID 25935853, 2015). "SW620 and HCT116 colorectal cancer cells were then transfected with mock or FoxM1 siRNA." (PMID 26264222, 2015). "Hence, we detected whether cell-surface HSPA5 is required for colorectal cancer cell migration and invasion induced by FOXM1." (PMID 27034162, 2016). "We next tested whether HSPA5 induced the expression of FOXM1 in colorectal cancer." (PMID 27034162, 2016).
colorectal cancer (continued). "Therefore, we investigated whether HSPA5 contributed colorectal cancer cells invasion and migration induced by FOXM1." (PMID 27034162, 2016). "Therefore, we investigated the relationship between FOXM1 with ER stress in colorectal cancer." (PMID 27034162, 2016). "Key transcription factor FOXM1 is overexpressed and promotes transcription of efflux transporter ABCC10 in vitro and in vivo for 5-FU-resistant colorectal cancer cells." (PMID 40777019, 2025). "MicroRNA-532-3p was ectopically overexpressed in colorectal cancer (CRC) cell lines, leading to reduced transcript and protein levels of FOXM1 and cyclin B1, a direct transcriptional target of FOXM1." (PMID 39272919, 2024). "In essence, microRNA-532-3p interacts with FOXM1 3’UTR, leading to decreased protein levels, thereby suppressing proliferation, migration, and invasion in colorectal cancer cells." (PMID 39272919, 2024). "In 5 independent gastric and colorectal cancer cohorts obtained from GEO and TCGA, RNF112 was negatively correlated with FOXM1 downstream genes, including CKS1, CCNB1, SKP2, and FN1." (PMID 37288663, 2023). "In the colorectal cancer cell lines HCT116, PF exerted anti-cancer effects via inhibiting cell growth and FoxM1 and increasing annexin-V-stained cells, cell cycle arrest at the G0/G1 phase, and the expression of p21 and p27." (PMID 38140352, 2023). "In late‐stage colorectal cancer, FOXM1D, a new isoform of FOXM1, promotes tumor metastasis by binding to and further activating ROCKs." (PMID 33314660, 2021). "Both FOXM1 and FOXQ1 mediate the tumor-suppressive activity of miR-342-3p in colorectal cancer cells." (PMID 30678643, 2019). "It has been documented that both FOXM1 and FOXQ1 serve as two targets of miR-342-3p in colorectal cancer." (PMID 30678643, 2019). "Initially, we profiled the expression of FOXM1 and TYMS in colorectal cancer cell lines, and also measured the expression of E2F1 as it is known to regulate TYMS and FOXM1 expression, independently." (PMID 30728402, 2019). "In human colorectal cancer (CRC), Gli1 regulates FOXM1 by directly binding to its promoter at BS4 (GCCCACCCA), which contributes to the proliferation of CRC cells." (PMID 30208972, 2018). "The results pointed to FOXM1 facilitated the activities of MMP2 and MMP9 at least partly dependent on cell-surface HSPA in colorectal cancer cells." (PMID 27034162, 2016). "We observed statistically significant positive correlations between FOXM1 and HSPA5 mRNA expression in colorectal cancer and adjacent normal tissue specimens (for tumor tissue: r = 0.445, P = 8.92×10−6; for normal tissue: r = 0.571, P = 5.28×10−9)." (PMID 27034162, 2016). "All above results indicated that FOXM1 binds to and activates HSPA5 promoter in colorectal cancer cells." (PMID 27034162, 2016). "In the present study, we demonstrated that FoxM1 and PTTG1 were concordantly up-regulated in colorectal cancers." (PMID 26264222, 2015). "To evaluate the baseline expression levels of FoxM1 in a series of human colorectal cancer cell lines, including HCT116, LOVO, DLD-1, SW480, SW620, we detected the mRNA and protein expression of FoxM1 by real-time PCR and Western Blot analyses, respectively." (PMID 25935853, 2015). "Boyden chamber assay indicated that FoxM1 and PTTG1 siRNAs attenuated migration and invasion of HCT116 and SW620 colorectal cancer cells." (PMID 26264222, 2015). "All these results clearly show that FoxM1 participates in EMT process and promotes the migration and matastasis in colorectal cancer cells." (PMID 25935853, 2015). "Bioinformatic analyses indicated that FoxM1 and PTTG1 are concordantly expressed in human colorectal cancer tissues, suggesting PTTG1 is a potential target of FoxM1." (PMID 26264222, 2015). "FoxM1 binds to PTTG1 promoter to promote PTTG1 transcription, and FoxM1-PTTG1 pathway promotes colorectal cancer migration and invasion." (PMID 26264222, 2015).
colorectal cancer (continued). "Boyden chamber assay indicated that both FoxM1 and PTTG1 regulate migration and invasion of HCT116 and SW620 colorectal cancer cells." (PMID 26264222, 2015). "The results indicate that most colorectal cancer cell lines, including SW620 and HCT116, express abundant FoxM1 mRNA." (PMID 26264222, 2015). "A colorectal cancer study demonstrated that SHH, Gli1, and FOXM1 mRNA expression levels were higher in colorectal adenocarcinomas than in adjacent normal colon tissue." (PMID 24325450, 2013). "In colorectal cancer, upregulation of PRDX3, induced by forkhead box M1 (FOXM1), could stimulate tumor cells to multiply and metastasize to distant locations by mitochondrial dysfunction." (PMID 41049446, 2025). "Based on GRN results, the functional relationship between two genes pairs ({IL2R, CYFIP2} and {FOXM1, PPARA}) in colorectal cancer was found to be statistically significant by the differential co-expression method; this result was also confirmed by GRN and GSEA methods." (PMID 33968339, 2021). "Similar to carboplatin effect, treatment of colorectal cancer cells with 5-FU resulted in FOXM1 upregulation without prominent cell death induction." (PMID 34262016, 2021). "FOXM1 expression was upregulated in colorectal cancer tissues compare to the adjacent non-tumor tissues." (PMID 29416616, 2018). "Our data showed that FOXM1 expression was upregulated in 28 colorectal cancer patients compared to the adjacent non-tumor tissues." (PMID 29416616, 2018). "Past studies have shown that FOXM1 was regulated by miR-149-5p in colorectal cancer and non-small cell lung cancer." (PMID 28902136, 2017). "Moreover, we observed statistically significant positive correlations between FOXM1 and MMP2 mRNA expression (n = 92, r = 0.6001, P = 2.71×10−10), between HSPA5 and MMP2 (n = 92, r = 0.403, P = 6.89×10−5) in colorectal cancer tissue specimens." (PMID 27034162, 2016). "Moreover, we observed statistically significantly positive correlations between FOXM1 and MMP2 mRNA expression, between HSPA5 and MMP2 in colorectal cancer tissue specimens." (PMID 27034162, 2016). "After normalization to cell viability, FOXM1 significantly enhanced cell migration and invasion, however depletion of HSPA5 using siRNA obviously attenuated cell migration and invasion induced by FOXM1 in colorectal cancer cells." (PMID 27034162, 2016). "Moreover, statistically significant positive correlations between FOXM1 and MMP2 mRNA expression, between HSPA5 and MMP2 were found in colorectal cancer tissue specimens." (PMID 27034162, 2016). "All above results pointed out FOXM1 correlated with HSPA5 in colorectal cancer was independent of hypoxia or ER stress by hypoxia." (PMID 27034162, 2016). "FoxM1 activates PTTG1 and promotes migration and invasion of colorectal cancer cells." (PMID 26264222, 2015). "The Forkhead box M1 (FOXM1) is an oncogenic transcription factor and plays a significant role in cell EMT, proliferation, metastasis in a multitude of human solid tumors including colorectal cancer (CRC)." (PMID 25935853, 2015). "Our data support the notion that the combined inhibition of EGFR and COX-2 in colorectal cancer cells disturbs FOXM1/β-catenin axis impacting CSC subpopulation, and therefore might improve the efficacy of existing therapies in colorectal cancer." (PMID 26107817, 2015). "To determine whether attenuated FoxM1 expression reversed the EMT process and further inhibited the migration and invasion in the colorectal cancer cells, we first explored the role of FoxM1 in CRC cell migration via the wound healing assay." (PMID 25935853, 2015). "Consistent with our finding that FOXM1 has a vital role in 5-FU resistance, a recent study has shown that FOXM1 can enhance 5-FU resistance through promoting the efflux of antitumour drugs by up-regulating the ABC subfamily C member 10 (ABCC10) expression in colorectal cancer cells." (PMID 30728402, 2019).
colorectal cancer (continued). "The expression of FOXM1 was higher in colorectal cancer samples compare to the non-tumor samples." (PMID 29416616, 2018). "Interestingly, interrogation of the expression levels of this gene panel (SOX4, FOXM1, and FOXQ1) in The Cancer Genome Atlas (TCGA) colorectal cancer data set (319 patients) revealed significantly poor disease-free survival in patients with elevated expression of this gene panel (P-Value: 0.0058)." (PMID 27119506, 2016). "Interestingly, interrogation of the expression of this identified gene panel (SOX4, FOXM1, and FOXQ1) in The Cancer Genome Atlas (TCGA) Colorectal cancer data set revealed significantly shorter disease-free survival in patients with elevated expression of these genes (Logrank Test P-Value: 0.00581)." (PMID 27119506, 2016). "For example, miR-342 may suppress the expression levels of FOXM1 and FOXQ1 through direct binding within the putative 3’-UTR binding sites of these genes, thereby inhibiting the proliferation, migration, and invasion of colorectal cancer cells in a xenograft animal model." (PMID 30360388, 2018). "In fact, both PKCδ and FOXM1 knockdown resulted in growth arrest, but not morphological changes, suggesting that other target molecules or signaling pathways are involved in the induction of the morphological differences of NC114‐treated colorectal cancer cells." (PMID 38425293, 2024).